GCG (glucagon)
Diseases named in the same sentence as GCG in open-access papers (continued):
Sharing a sentence is not in itself a finding about the gene and the disease.
Hypoglycemia (continued). "In addition to suppressing glucagon, the slowing of gastric emptying may attenuate the counterregulatory acceleration of gastric emptying by hypoglycaemia, which could increase the risk of hypoglycaemia, as observed in a trial with liraglutide." (PMID 36194250, 2022). "In T1D, deficiency of the secretory response of glucagon to hypoglycemia is an early acquired (<2 years of onset) abnormality of counter-regulation and leads to severe hypoglycemia, which may in part be explained by the major structural and functional changes that occur to islets in T1D." (PMID 34787082, 2021). "Our results show that the commonly prescribed cardiovascular medications bumetanide and captopril, the analgesic acetaminophen, and the proton pump inhibitor pantoprazole may cause sufficiently severe hypoglycemia necessitating glucose infusion or glucagon injection at a hospital." (PMID 34040513, 2021). "In addition, we investigated the modulatory effects of exogenous (CDCA) and endogenous bile acids (by COL administration) on meal-induced plasma concentrations of glucose, including the risk of hypoglycemia, and other glucoregulatory hormones including insulin, glucagon, CCK, neurotensin and FGF-19." (PMID 34084153, 2021). "Our findings suggest that when used in combination with DPP-4i′s, bumetanide, captopril, acetaminophen, cotrimoxazole, and pantoprazole may increase the risk of hypoglycemia more than twice and require the intervention of glucose infusion or glucagon injection." (PMID 34040513, 2021). "Importantly however, our results indicate that harnessing the mechanisms of amplifying glucagon signaling through the hepatic cAMP-PKA-CREB signaling nexus is a viable option with a plethora of potential for developing therapies for HI associated hypoglycemia." (PMID 32735622, 2020). "However, it is difficult to justify a control arm for standard of care medication (even though efficacy of dose titration of glucagon remains unproven) in a disease where medications are simultaneously used in order to reduce the risk of hypoglycemia in the shortest possible time." (PMID 33013678, 2020). "During his first week of life, a diagnostic fasting test revealed hypoglycemia following only 3.5 hr of fasting (plasma glucose 35 mg/dl, 2.0 mmol/l) with suppressed beta‐hydroxybutyrate and an inappropriately large glycemic response to glucagon (delta 82 mg/dl), confirming HI." (PMID 31464105, 2019). "Opposed to the artificial pancreas, which administers either insulin or glucagon depending on the blood glucose level, we investigated whether coadministration of a fixed ratio of the two hormones could reduce the risk of hypoglycemia when treating diabetic rats." (PMID 29595915, 2018). "As demonstrated in a previous model-based simulation study (König and Holzhütter, 2012), exposing the permanently glucose-releasing “starved” liver of the diabetic patient to a rigorous insulin treatment at persistently elevated glucagon level may increase the risk of severe hypoglycaemia." (PMID 30631280, 2018). "Furthermore, PPY inhibits glucagon secretion and rarely causes hypoglycemia." (PMID 28228865, 2017). "However, high doses of glucagon may paradoxically stimulate insulin secretion and increase glucose infusion requirements or cause further, rebound hypoglycaemia." (PMID 26316429, 2015). "In all challenges, glucagon levels during hypoglycemia were higher with SSTR2a administration compared to controls." (PMID 41502124, 2026). "This work aimed to evaluate the effect of exogenous GLP-2 on plasma glucagon levels during hypoglycemia, euglycemia, and hyperglycemia in healthy male volunteers." (PMID 41541287, 2026). "In T1D, where exogenous insulin is required, protein’s glucagon-stimulating properties can be leveraged to prevent delayed or overnight hypoglycemia, assist during prolonged activity, or enhance mild hypoglycemia treatment." (PMID 41602572, 2026).
Hypoglycemia (continued). "In these participants, glibenclamide (0.3-0.6 mg/day for 14-18 days) raised circulating glucagon during hypoglycaemia by 125-150%; this correlated with reduced glucose infusion requirements, reflecting stimulation of endogenous glucose production." (PMID 42155411, 2026). "It has also been shown that the glucagon response to protein is preserved when glucagon counterregulation to hypoglycemia is abolished, making free amino acids an effective rescue treatment to mild hypoglycemia." (PMID 41602572, 2026). "It has long been known that the glucagon response to protein intake is preserved in T1D, even when the counterregulatory processes of glucagon to hypoglycemia or exercise are diminished." (PMID 41602572, 2026). "A total of 62 subjects undergoing growth hormone function tests were retrospectively enrolled and stratified by stimulation type: levodopa (n=28), insulin-induced hypoglycemia (n=7), glucagon (n=20), and octreotide (n=7)." (PMID 41814904, 2026). "In contrast, mean peak glucagon response occurred in response to dosing in the SSTR2a group, and remained elevated during hypoglycemia." (PMID 41502124, 2026). "Conversely, in an extensive study in mice, GLP-2 was unable to stimulate glucagon secretion from perfused pancreatic islets in vitro or during insulin-induced hypoglycemia in vivo." (PMID 41541287, 2026). "Here, we report a single-molecule prodrug design that enables glucose-responsive activation of a glucagon analog for hypoglycemia protection." (PMID 41810046, 2026). "Early efforts to target glucagon signaling achieved glucose lowering but were limited by adverse effects, including hypoglycemia and hepatic toxicity." (PMID 41575482, 2026). "Here, using a specific and sensitive glucagon sandwich enzyme-linked immunosorbent assay (ELISA), we reevaluated the effect of exogenous GLP-2 on plasma glucagon levels during hypoglycemia, euglycemia, and hyperglycemia in lean, healthy, young men." (PMID 41541287, 2026). "The primary objective was the change in glucagon response during clamp-induced hypoglycemia from plasma glucose (PG) 100 mg/dL to nadir PG (45 mg/dL)." (PMID 40964167, 2025). "In contrast, hypoglycemia promotes glucagon secretion through activation of the sympathetic nervous system and elevated circulating amino acid levels." (PMID 40822953, 2025). "Sympathetic innervation of the islets plays a role in the glucagon response following insulin-induced hypoglycemia." (PMID 40940782, 2025). "Acute complications such as hypoglycemia and diabetic ketoacidosis are managed through fluid resuscitation, electrolyte correction, insulin infusion, and prompt glucose or glucagon administration." (PMID 40716044, 2025). "Given its role, glucagon is now being considered a potential therapeutic agent for treating hypoglycemia in individuals with T1DM." (PMID 39996055, 2025). "In the present study, we show that ATP8B1 deficiency in mice leads to glucagon resistance and fasting hypoglycaemia and identify that increased PDE4 expression in human and mouse ATP8B1‐deficient hepatocytes mediates this glucagon resistance." (PMID 40851490, 2025). "Dasiglucagon, a synthetic glucagon analog, represents a promising candidate for the treatment of severe hypoglycemia in patients with congenital hyperinsulinism (CHI)." (PMID 40300042, 2025). "We present a patient with a glucagon-secreting pNET with metachronous insulin hypersecretion in the context of disease progression, which lead to treatment-refractory hypoglycemia and death." (PMID 41561059, 2025). "In one study, individuals on an LCD exhibited a blunted glycemic response to glucagon during insulin-induced hypoglycemia." (PMID 40573112, 2025). "Increased plasma glucagon leads to an increase in hepatic glucose production in situations of hypoglycemia, counteracting the hypoglycemic effects of insulin." (PMID 39549141, 2025).
Hypoglycemia (continued). "At present, the only alternative to oral carbohydrate intake for medically treating hypoglycemia is glucagon therapy." (PMID 41510436, 2025). "In clinical settings, intravenous (IV), subcutaneous (SC), and IM glucagon are available for the treatment of mild-to-severe hypoglycemia." (PMID 40585626, 2025). "Previous studies have found that 600 mg of GABA restores the vitality of beta cells, resists streptozotocin toxicity, and increases the glucagon, adrenaline, growth hormone, and cortisol responses to hypoglycemia by over two-fold." (PMID 40869014, 2025). "Prior reports suggest the modest effectiveness of recombinant human GH, glucocorticoids, and continuous glucagon infusion in hypoglycemia management from NICTH." (PMID 41209155, 2025). "We investigated the response of glucagon and other counterregulatory hormones, insulin and C-peptide concentration, hypoglycemic symptoms, and cognitive function during clamp-induced hypoglycemia in people with T2D treated with tirzepatide versus placebo." (PMID 40964167, 2025). "This mechanistic uncoupling between L-type VGCC-driven electrical activity and RyR-mediated CICR highlights a specialized signaling pathway in α-cells, ensuring precise glucagon release during hypoglycemia." (PMID 40422193, 2025). "According to our data, glucagon provides a useful option to treat fasting—induced hypoglycemia in a home setting for adults with type 1 diabetes who are fasting during Ramadan." (PMID 40364253, 2025). "Clinical trials of dual-hormone systems have consistently demonstrated that adding glucagon reduces the incidence of hypoglycaemia compared with insulin-only systems, particularly in high-risk or high-activity scenarios such as exercise and overnight periods." (PMID 40718205, 2025). "As a crucial regulator of glucose homeostasis, glucagon stimulates hepatic gluconeogenesis and glycogenolysis, enabling rapid glucose mobilization during hypoglycemia." (PMID 40822953, 2025). "Secondly, excess insulin inhibits alpha cells, reducing glucagon’s response to hypoglycemia, which in turn decreases glucagon secretion and exacerbates blood glucose decline." (PMID 41573194, 2025). "Early devices operated to suspend insulin delivery at predefined thresholds, but newer systems enable modulation of basal insulin dosing in response to real-time glucose trends and even incorporate glucagon to prevent hypoglycaemia." (PMID 40718205, 2025). "In normal physiology, glucagon plays an important role in regulating blood glucose levels to prevent hypoglycemia by acting as a counterregulatory hormone, raising blood glucose levels to prevent low blood sugar." (PMID 41510436, 2025). "Ghrh-R was observed to inhibit baseline glucagon secretion, yet it up-regulated hormone release during hypoglycemia." (PMID 40688570, 2025). "Under normal physiological conditions, glucagon is released from pancreatic alpha cells to elevate circulating glucose levels in response to hypoglycemia." (PMID 41308986, 2025). "As a result, important counterregulatory responses—such as glucagon release and sympathetic activation—remain more intact if hypoglycemia occurs." (PMID 40003896, 2025). "LCD: ↑ TIR (83% vs. 72%, p = 0.004), ↓ hypoglycemia (3.3% vs. 8.0%, p = 0.03), ↓ GV (SD 1.9 vs. 2.6 mmol/L; CV 27.7% vs. 35.4%, p = 0.02); MG ↔; fasting ketones, glucagon, FFAs." (PMID 41228423, 2025). "As new methods of delivering and administering glucagon are created, including bihormonal hybrid closed—loop devices, these data offer justification and rationale for using glucagon in managing hypoglycemia during fasting periods in individuals with T1D." (PMID 40364253, 2025). "Recurrent hypoglycemia can trigger fluctuations in counter-regulatory hormones (adrenaline, cortisol, glucagon) and compensatory hyperinsulinemia." (PMID 41585801, 2025). "The response of the key counterregulatory hormone glucagon to induced hypoglycemia was maintained with tirzepatide." (PMID 40964167, 2025).
Hypoglycemia (continued). "Instead, hypoglycemia was marked by increases in glucagon levels and severe metabolic dysregulation in the liver and spleen." (PMID 40702267, 2025). "Further data indicated the possibility of using MDG therapy to avoid hypoglycemia during physical activity through the use of a G—Pen Mini with a 150 mg dose of stable glucagon." (PMID 40364253, 2025). "SGLT2 inhibitors promote glucosuria by inhibiting glucose reabsorption in the proximal renal tubule, and the associated suppression of insulin secretion and stimulation of glucagon secretion protect against hypoglycemia." (PMID 40731782, 2025). "This leads to hypoglycaemia, suppressed glucagon secretion, reduced hepatic glucose output, and decreased levels of growth hormone and IGF‐I due to feedback inhibition." (PMID 40697895, 2025). "In the postprandial state, GIP stimulates insulin after a meal and glucagon secretion during eu- and hypoglycaemia." (PMID 40218856, 2025). "Parental education on glucose monitoring, emergency treatment administration (glucagon), and recognition of hypoglycemia symptoms is essential to optimize outpatient follow-up for patients with CHI." (PMID 40904956, 2025). "In each sex, gene knockdown up- or down-regulated baseline glucagon and growth hormone (GH) release, but hypoglycemia reversed the direction of Ghrh-R control of each hormone." (PMID 40688570, 2025). "In this context, counter-regulatory hormones, such as glucagon, cortisol, and epinephrine, prevent and correct hypoglycemia." (PMID 40932945, 2025). "In conclusion, the response of the key counterregulatory hormone glucagon to induced hypoglycemia was maintained with tirzepatide in people with T2D." (PMID 40964167, 2025). "In human type 1 diabetes there is an impaired glucagon response to hypoglycemia, and death due to iatrogenic hypoglycemia has been estimated to be as high as 10%7." (PMID 40473678, 2025). "Intramuscular glucagon is widely used for emergency treatment of hypoglycaemia with a half-life after intramuscular injection of only 26 min, so a one-day interval between GST and ITT was fully adequate for a complete wash-out." (PMID 41010774, 2025). "Previously, the mini‐dose glucagon as an adjunct to MDI + CGM for preventing fasting‐related hypoglycaemia was explored." (PMID 40620207, 2025). "Since the 1970s, glucagon has been used as a cornerstone therapy for severe hypoglycemia outside of emergency medical settings." (PMID 41510436, 2025). "A concern regarding the use of a GLP-1RA in patients with T1D in clinical practice would be the risk of hypoglycemia, as GLP-1RAs not only enhance endogenous insulin secretion but also suppress glucagon release, a major counter-regulatory hormone." (PMID 40760325, 2025). "Traditional emergency glucagon kits require reconstitution of a crystallized powder with diluent, producing a single 1 mg solution intended for the treatment of severe hypoglycemia." (PMID 41510436, 2025). "Repeated episodes of severe hypoglycemia led to the patients’ admission for implementation of other measures such as IV dextrose, glucagon infusion, short acting subcutaneous SSA and high dose corticosteroids, which still proved insufficient." (PMID 41561059, 2025). "We report the case of a patient with a metastatic glucagon-secreting pNET who, after 14 years of disease and multiple treatment lines, developed insulin hypersecretion and severe, treatment-refractory hypoglycemia." (PMID 41561059, 2025). "We present a case of a patient with a stage IV glucagon-producing pNET that, after 14 years and different treatment modalities, presented with new onset insulin secretion and refractory hypoglycemia." (PMID 41561059, 2025). "Its secretion is tightly regulated by blood glucose levels, with hypoglycemia acting as a potent trigger for glucagon release." (PMID 41510436, 2025).
Hypoglycemia (continued). "Typically, when the plasma glucose concentration decreases, first, pancreatic beta cells stop insulin, followed by increased secretion of glucagon and adrenaline to prevent hypoglycemia." (PMID 38334891, 2024). "Another study demonstrated that expression of Agpat5 in agouti-related peptide neurons in the hypothalamus contributes to hypoglycemia-induced glucagon secretion." (PMID 39608054, 2024). "The physiological function of glucagon is elevating blood glucose during hypoglycemia by stimulating hepatic glucose production and inhibiting glycogen synthesis." (PMID 39337311, 2024). "An unexpected finding in the present study was the significant increase in plasma glucagon during hypoglycaemia following RT-CGM+HIIT." (PMID 38010533, 2024). "Studies on mice revealed the presence of V1bR mRNA at the pancreatic α-cells and showed that enhanced release of AVP and stimulation of V1bR play a significant role in the elevation of glucagon release during insulin-mediated hypoglycemia." (PMID 39769071, 2024). "This is in contrast to the GCG-micelle-treatedmice in which baseline glycemia (130 mg/dL) was restored by 120 min.Overall, in vivo efficacy studies confirmed thatthe glucagon micelle can safely prevent and reverse deep hypoglycemia." (PMID 39634211, 2024). "Briefly, hypoglycaemia triggers a reduction in insulin secretion and an increase in glucagon secretion from the pancreas leading to increased glycogen breakdown and glucose production in the liver." (PMID 38392992, 2024). "They demonstrated that this metformin-like compound amplified peak plasma glucagon levels in response to hypoglycemia in healthy rats." (PMID 38323079, 2024). "This study revealed that the incidence of hypoglycemia after mitral valve repair was 14.2%, and plasma glucagon concentrations increased in these dogs, whereas serum insulin concentrations decreased compared with preoperative levels." (PMID 38393097, 2024). "In summary, we show here that an SSTR2 antagonist can improve the glucagon counterregulatory response to insulin-induced hypoglycemia and prevent, or at least delay, the onset of hypoglycemia by up to −40 min in a rat model of T2D." (PMID 38510652, 2024). "For example, GIP stimulates glucagon secretion from pancreatic α-cells in hypoglycemia in healthy persons but, in T2D, the glucagonotropic function of GIP is dysregulated." (PMID 39594592, 2024). "A primary concern other clinicians has is the belief that a KD depletes glycogen stores before ketone production occurs, potentially rendering glucagon injections ineffective during severe hypoglycemia." (PMID 39539363, 2024). "In the case of severe hypoglycemia, when the patient cannot consume carbohydrates, the administration of glucagon intramuscularly or intranasally is indicated." (PMID 39330031, 2024). "Data moreover substantiate VMN SF-1 regulation of circulating corticosterone, glucagon, and GH concentrations during eu- and hypoglycemia." (PMID 39024550, 2024). "During hypoglycemia,however, the micelle disassembles into its original, unimeric state,revealing the active glucagon conjugate." (PMID 39634211, 2024). "Systems that deliver glucagon in addition to insulin can be more effective during, and in preventing hypoglycemia episodes than insulin delivery alone." (PMID 39390689, 2024). "In pediatric PWD, severe hypoglycemia is characterized by convulsions, coma, or other neurological symptoms of neuroglycopenia, and it requires therapy with glucagon or IV glucose." (PMID 38894740, 2024). "During hypoglycemia, both groups showed comparable rates of glycemic recovery and stomach emptying; glucagon and other counterregulatory hormone levels were unaffected by liraglutide." (PMID 39273299, 2024). "Research has shown that hypoglycemia increases levels of hormones like glucagon, cortisol, and growth hormone, which can elevate heart contractility and oxygen demand, potentially leading to adverse cardiovascular effects." (PMID 39749314, 2024).